NLK (nemo like kinase)
Diseases named in the same sentence as NLK in open-access papers (continued):
Sharing a sentence is not in itself a finding about the gene and the disease.
ischemic stroke (1 paper, 2016). A stroke disorder caused by obstruction of blood flow to the brain, due to thrombotic (local blood clot formation) or embolic (due to a blood clot or other material traveling from another site) event. "Specifically, the expression levels of the genes CASP3 and NLK were significantly lower in ischemic stroke patients than in controls and were negatively correlated with let-7e-5p expression." (PMID 27776139, 2016). "In addition, in human whole blood samples, the mRNA levels of both CASP3 and NLK were lower in ischemic stroke patients than in control subjects, and they were both negatively correlated with let-7e-5p expression." (PMID 27776139, 2016). "Moreover, let-7e-5p regulates the expression of CASP3 and NLK and may be involved in the pathogenesis of ischemic stroke." (PMID 27776139, 2016). "Bioinformatics prediction and target gene expression analysis showed that let-7e-5p may be involved in the pathogenesis of ischemic stroke by regulating CASP3 and NLK expression, two genes enriched in the MAPK signaling pathway." (PMID 27776139, 2016).
lung adenocarcinoma (1 paper, 2024). A carcinoma that arises from the lung and is characterized by the presence of malignant glandular epithelial cells. "Regarding the MAPK signaling KEGG pathway, more specifically the p38 MAPK pathway, contains the NLK gene that is a precursor for the Wnt pathway, which has been previously demonstrated to be key for metastasis and tumor proliferation in lung adenocarcinoma." (PMID 39917181, 2024).
lymph node metastasis (1 paper, 2024). "Similarly, high expression of NLK was positively correlated with tumor size (p<0.001), lymph node metastasis (p<0.001), UICC stage (p=0.009), CA19-9 value (p=0.03), and vascular invasion (p=0.04)." (PMID 39097735, 2024).
melanoma (1 paper, 2020). A malignant, usually aggressive tumor composed of atypical, neoplastic melanocytes. "Recently, it was shown that NLK expression in melanoma correlates with vascular endothelial growth factor receptor 2 (VEGFR2)-related microvessel formation and melanoma metastasis." (PMID 33276680, 2020). "NLK was found to be expressed in biopsied tissues of melanoma patients, but was expressed significantly lower in metastatic melanoma, implying that NLK may serve as a new prognostic marker." (PMID 33276680, 2020).
myeloid leukemia (1 paper, 2020). A clonal proliferation of myeloid cells and their precursors in the bone marrow, peripheral blood, and spleen. "The assay was validated in Kp53A1 myeloid leukemia cells and specificity of the NLK antibody was also confirmed." (PMID 32620751, 2020).
Nance-Horan syndrome (1 paper, 2020). A syndrome characterized by the association in male patients of congenital cataracts with microcornea, dental anomalies and facial dysmorphism. "An interaction network analysis of the top 100 DM CpG sites showed five common regulator genes: nemo-like kinase (NLK), calcium/calmodulin-dependent protein kinase 1 (CAMKK1), lysophosphatidic acid receptor 2 (LPAR2), caspase 1 (CASP1), and Nance-Horan syndrome (NHS)." (PMID 32605309, 2020).
proteinopathies (1 paper, 2025). "Introduces a novel mechanism for nucleocytoplasmic transport defects in TDP43 proteinopathies and provides a framework for targeting NLK in neurodegenerative diseases." (PMID 40553568, 2025). "Targeting NLK protein levels or kinase activity could thus represent a potentially novel therapeutic approach for ALS, FTLD-TDP, and other TDP43 proteinopathies." (PMID 40553568, 2025). "Importantly, NLK is upregulated selectively in affected neurons from patients with ALS and correlates with TDP43 mislocalization, implicating NLK as a key determinant of disease pathophysiology and highlighting NLK as a promising therapeutic target for ALS and related TDP43 proteinopathies." (PMID 40553568, 2025).
retinal degeneration (1 paper, 2015). Degeneration of the retina. "Co-expression of NLK-WT enhanced the retinal degeneration phenotype and, more strikingly, dramatically increased the mutant AR aggregation detected by immunoblot (lane 4 vs lane 6)." (PMID 26308581, 2015). "Importantly, we also found that expression of kinase-dead NLK-KN did not enhance the retinal degeneration phenotype or mutant AR aggregation (lane 4 vs lane 7), a finding consistent with our cell culture data." (PMID 26308581, 2015).
Sepsis (1 paper, 2026). Sepsis is defined as life-threatening organ dysfunction caused by a dysregulated host response to infection. "Integrated analyses of bulk (GSE65682) and single-cell (GSE167363) transcriptomic datasets from patients with sepsis revealed elevated NLK expression in monocytes, strongly associated with PANoptotic effectors and adverse outcomes." (PMID 41674095, 2026). "Collectively, these findings identify NLK as a regulatory rheostat of Caspase-8-associated PANoptosis in sepsis and highlight the NLK-Caspase-8 axis as a potential therapeutic target for fine-tuning sepsis-associated inflammatory cell death." (PMID 41674095, 2026). "Here, we identify Nemo-like kinase (NLK) as a novel regulator of Caspase-8-mediated PANoptotic signalling in sepsis." (PMID 41674095, 2026).
spinobulbar muscular atrophy (1 paper, 2025). "NLK depletion mitigates disease phenotypes not only in Drosophila and murine models of ALS but also in murine models of spinobulbar muscular atrophy and spinocerebellar ataxia." (PMID 40553568, 2025).
spinocerebellar ataxias (1 paper, 2020). "NLK-deficient animals on a C57BL/6 background died in the third trimester of pregnancy, while mice on a 129/Sv background survived up to 4–6 weeks after birth, but displayed a pronounced cerebellar ataxia." (PMID 33276680, 2020).
tumor (36 papers, 2013 to 2026). "Circ‐0009092 regulates STAT3 modification and reduces CCL2 expression by targeting the miR‐665/NLK signaling axis, which inhibits tumor‐associated macrophage aggregation and slows down the EMT progression of tumor." (PMID 39584047, 2024). "NLK knockdown cells exhibit a decrease in tumor formation, while NSCLC patients show an increase in NLK expression, which was also associated with the T-stage of the tumor." (PMID 37627077, 2023). "Taken together, our data demonstrated that circ_0009092/miR-665/NLK suppresses tumor progression and TAMs recruitment by inhibiting the Wnt/β-catenin signaling pathway in the CRC." (PMID 38008713, 2023). "NLK directly interacted with STAT3 and decreased the CCL2 expression, inhibiting the recruitment of tumor-associated macrophages (TAMs) in the TME." (PMID 38008713, 2023). "Circ_0009092/miR-665/NLK suppressed tumor EMT, proliferation, migration, and invasion by acting on the Wnt/β-catenin signaling pathway." (PMID 38008713, 2023). "We carried out a co-immunoprecipitation (CoIP) assay in tumor cells using the antibody against STAT3 or NLK." (PMID 38008713, 2023). "On the whole, ASMTL‐AS1 transferred by exosomes enhances the malignancy of residual HCC tumours after insufficient RFA through NLK/YAP signalling." (PMID 32722884, 2020). "By binding to the specific 36G46A micro-domain of HOTAIR, ADQ efficiently abrogate the HOTAIR/EZH2 interaction, thereby inhibiting H3K27-mediated tri-methylation of the NLK and consequently inhibiting tumor metastasis." (PMID 30764859, 2019). "Of the DE miRNAs, there was a marked number targeting critical tumor suppressors (PTEN, AXIN1, ATM, NLK) and critical proto-oncogenes and tumor promoting genes such as MYC." (PMID 29132323, 2017). "Central to all these findings, we observed the downregulation of ATM and NLK genes, which represent important regulators in response to DNA damage in eBL tumor cells." (PMID 29132323, 2017). "Recent studies show that NLK expression is altered in various types of human cancer, acting as either an oncogene or tumor suppressor depending upon tumor type." (PMID 27036119, 2016). "In PCa, NLK appears to act as a tumor suppressor, with mRNA expression decreasing concomitant with the development of cancer." (PMID 27036119, 2016). "This approach allowed us to identify NLK as a candidate tumor suppressor and a key regulator of GBM pathogenesis." (PMID 26023737, 2015). "To determine the role of NLK in tumor propagation in vivo, we generated intracranial xenograft tumor models derived from the control and NLK-overexpressing GBM cells." (PMID 26023737, 2015). "Quantitation of immunohistochemical analyses using the sections derived from 88 GBM specimens and non-tumor brain tissues revealed significant difference in NLK expression." (PMID 26023737, 2015). "Results from the MTT assays and limiting dilution sphere forming assays indicated that NLK K/N is ineffective to elicit NLK-mediated responses, indicating that the tumor-suppressive role of NLK in GBM is through its kinase activity-dependent manner." (PMID 26023737, 2015). "Here, we have identified NLK as a putative tumor suppressor gene and demonstrated that NLK plays a critical role in tumor restriction through regulation of Wnt/beta-catenin pathway and mesenchymal activity in GBM." (PMID 26023737, 2015). "To validate RNAi screening results, we further inhibited NLK by shRNA-mediated knockdown and evaluated its effects on tumor growth." (PMID 26023737, 2015).
tumor (continued). "As previous studies have shown that MXI1 and PTEN were both involved in GBM as tumor suppressor genes for their abilities to regulate tumor cell growth, migration, and apoptosis, we decided to focus on NLK." (PMID 26023737, 2015). "In our study, NLK knockdown significantly inhibited the tumor sphere formation from A549 cells (p = 0.012, p < 0.001 for each." (PMID 26503334, 2015). "Hematoxylin and eosin (H&E) staining of mouse brain sections showed a significant difference in tumor volumes between the control and the NLK overexpression group." (PMID 26023737, 2015). "Then, tumor xenograft mouse models revealed that NLK knockdown cells had a reduced ability for tumor formation compared with the control group in vivo." (PMID 26503334, 2015). "shRNA mediated knockdown of NLK in A549 cells resulted in a markedly reduced growth rate (p < 0.001) and tumor weight (p < 0.001) compared with tumors formed from A549-scramble cells." (PMID 26503334, 2015). "The overexpression of NLK suppressed tumor cell proliferation and transforming potential via the transcriptional inhibition of c-Myb." (PMID 23935942, 2013). "Targeted disruption of Nemo-like kinase inhibits tumor cell growth by simultaneous suppression of cyclin D1 and cyclin-directed kinases in human HCC." (PMID 23951254, 2013). "Further studies will focus on the molecular mechanisms of NLK-induced tumor development, as well as on developing strategies to upregulate the protein or modulate its function for potential therapeutic applications." (PMID 23935942, 2013). "In most specimens, the proportion of NLK-positive tumor cells was negatively correlated with the proportion of c-Myb-positive and Ki-67-positive tumor cells." (PMID 23935942, 2013). "In SMAD-independent manner, tumor suppressive functions of TGFß involve TAK1/NLK activation-mediated antagonism of Wnt/ß-catenin signaling limiting the stem cell population." (PMID 23799116, 2013). "We further examined the expression of NLK in tumor tissues of CRC." (PMID 38008713, 2023). "The NLK mRNA levels were significantly lower in 80 tumor samples than that in ANT." (PMID 38008713, 2023). "In addition, dysregulation in NLK expression can affect the development and progression of various diseases, including cancer, where NLK has been found to act as a tumour suppressor or oncogene depending on the tumour type." (PMID 33276680, 2020). "ADQ specifically bound the 36G46A site in the 5′ functional domain of HOTAIR and efficiently disrupted the interaction between HOTAIR and EZH2 both in vitro and in orthotopic tumor mouse models, thereby reducing the H3K27-mediated tri-methylation of NLK and consequently inhibiting tumor metastasis." (PMID 30764859, 2019). "The observed NLK downregulation in eBL tumor cells could also be critical to aid in tumor cell escape from certain death initiated by DNA damage (that results in the c-myc-Igh chromosomal translocation) and oncogene-induced apoptotic stress." (PMID 29132323, 2017). "NLK may perform this tumor suppressive function in PCa through its suppression of the NF-κB- and CREB-mediated transcription, and interestingly, the promoter region of the human Nurr1 gene contains both NF-κB- and CREB-binding sites." (PMID 27036119, 2016). "In a recent study, the expression levels of NLK were significantly upregulated in CRC tissues compared to which in matched non-tumor tissues, and the NLK expression was significantly correlated with the clinicopathological features including the depth of tumor invasion." (PMID 26084278, 2015). "In addition, both NLK knockdown and metformin treatment reduced the tumor sphere formation capacity and percentage of CD133+ cells." (PMID 26503334, 2015). "To examine whether tumor-suppressive role of NLK is dependent on kinase activity, we overexpressed NLK kinase-inactive mutant (NLK K/N) in GBM cells and determined its effects on short-term proliferation and clonogenic growth of GBM cells." (PMID 26023737, 2015).
tumor (continued). "Together, these results support that NLK inhibition facilitates in vivo tumor growth." (PMID 26023737, 2015). "However, contrasting studies demonstrate that NLK expression is lower in tumors compared with normal tissues, and moreover, that induction of NLK can induce apoptosis of tumor cells." (PMID 26503334, 2015). "The tumor suppressor function of NLK was recently established." (PMID 24816797, 2014). "We also show that miR-409-3p may function as an tumor suppressor by directly targeting NLK." (PMID 26084278, 2015). "Notably, expression of NLK was correlated with NSCLC Tumor size (T stage) (p = 0.016)." (PMID 26503334, 2015). "Specifically, ASGR1 interacts with Nemo-like kinase (NLK) to inhibit glycoprotein 130/janus kinase 1 (GP130/JAK1)-mediated STAT3 phosphorylation, thereby blocking the activation of STAT3-related pro-tumor signaling pathways." (PMID 40852369, 2025). "In Miapaca-2 cells, compared to MSI2-Ctrl, the invasive and migratory abilities of tumor cells were reduced in the MSI2-Sg group, but partially rescued after co-transfection with Lv-NLK." (PMID 39097735, 2024). "In conclusion, this research illustrated the participation of an ASMTL‐AS1/miR‐342‐3p/NLK/YAP signalling in reinforcing the malignancy of HCC cells, especially those in residual tumours after insufficient RFA." (PMID 32722884, 2020). "In contrast, NLK also appears to function as a tumor suppressor in HCC because a study has reported that miR-181 induces HCC cell quantity and tumor initiating ability through direct inhibition of NLK mRNA translation." (PMID 29977206, 2018). "Enrichment of pathways showed the interaction of these miRNAs with marked tumor suppression (PTEN, AXIN1, ATM, NLK), and important proto-oncogenes and tumor-promoting genes as MYC." (PMID 30201877, 2018). "First, we determined the expression levels of NLK protein in matched GBM and adjacent non-tumor brain specimens by tissue microarray (TMA)." (PMID 26023737, 2015). "Knockdown of NLK in both A549 and SK-MES-1 cells reduced their proliferation in vitro, as well as tumor growth in vivo." (PMID 26503334, 2015). "Restoration of NLK inhibited WNT and mesenchymal activities, decreased clonogenic growth and survival, and impeded tumor growth in vivo." (PMID 26023737, 2015). "Immunohistochemical (IHC) analysis revealed that NLK expression was up-regulated in NSCLC cases (p < 0.001) and correlated with tumor T stage (p < 0.05)." (PMID 26503334, 2015). "Thus, they can suppress β-catenin levels by increasing nemo-like kinase (NLK) and adenomatous polyposis coli 2 (APC2) expressions, respectively, which eventually prohibit tumor progression in vivo." (PMID 34073224, 2021). "As a result, more YAP was phosphorylated at Ser128 and therefore induced more YAP trans‐locating to nucleus in tumours from patients after insufficient RFA than in those from patients without RFA due to higher NLK protein." (PMID 32722884, 2020). "The results indicate that compared with the non-tumorous adjacent tissue, NLK expression was dramatically lower and Nurr1 expression much higher in the tumor tissues." (PMID 27036119, 2016). "To identify a better therapeutic target for this highly malignant tumor, we first reported the novel mechanism that long non-coding RNA HOTAIR regulates cell cycle progression and invasion through an NLK/β-catenin axis in GBM samples with different EGFR statuses." (PMID 25823657, 2015). "We plated tumor cells at the clonal density ranging from 1 to 50 cells per well and monitored clonogenic growth of tumor cells with or without overexpression of NLK." (PMID 26023737, 2015). "NLK was essential for CRC tumor initiation but not required for tumor progression in murine CRC model." (PMID 26084278, 2015). "In addition, NLK regulates phosphorylation and O-GlcNAcylation of STAT3 by binding to STAT3, thereby inhibiting CCL2 expression, in which it inhibits macrophage recruitment in the tumor microenvironment (TME)." (PMID 38008713, 2023).
tumor (continued). "In contrast to high NLK expression in non-tumor tissues, GBM tissues have little or no expression." (PMID 26023737, 2015).